ERP27 (endoplasmic reticulum protein 27)
Description:
Specifically binds unfolded proteins and may recruit protein disulfide isomerase PDIA3 to unfolded substrates. Binds protein substrates via a hydrophobic pocket in the C-terminal domain. May play a role in the unfolded stress response.
Synonyms: C12orf46; FLJ32115; PDIA8
Tractability: Antibody: UniProt predicts a signal peptide or a membrane-spanning region.
Gene: Protein-coding gene on chromosome 12 (14,914,039 to 14,938,537, reverse strand). Ensembl gene ENSG00000139055.
Subcellular location: Endoplasmic reticulum lumen
Gene Ontology:
Molecular function: protein binding; protein disulfide isomerase activity
Biological process: protein folding
Cellular component: endoplasmic reticulum lumen
Genetic constraint (gnomAD): Loss-of-function variants: 21 observed, 28.22 expected, observed/expected ratio (o/e) 0.74, 90% interval 0.53 to 1.07. The synonymous counts are far from expectation, so gnomAD's model fits this gene poorly and the ratio says little. Missense variants: 361 observed, 342.64 expected, observed/expected ratio (o/e) 1.05, 90% interval 0.97 to 1.15. Synonymous variants: 159 observed, 125.5 expected, observed/expected ratio (o/e) 1.27, 90% interval 1.11 to 1.45.
Homologues: Orthologues: chimpanzee ERP27 (97% identical), macaque ERP27 (93% identical), pig ERP27 (74% identical), dog ERP27 (73% identical), rabbit ERP27 (73% identical), guinea pig ERP27 (69% identical), mouse Erp27 (64% identical), rat Erp27 (63% identical), tropical clawed frog erp27 (38% identical), Caenorhabditis elegans pdi-2 (27% identical), Caenorhabditis elegans pdi-1 (24% identical), Drosophila melanogaster Pdi (22% identical), and 5 more. Paralogues in human: P4HB (29% identical), PDIA2 (27% identical), PDILT (26% identical), PDIA3 (20% identical), PDIA4 (19% identical), TMX3 (17% identical), TXNDC11 (14% identical), ERP44 (13% identical), TXNDC5 (10% identical), PDIA5 (10% identical), PDIA6 (7% identical), TMX1 (7% identical), and 1 more.
Diseases named in the same sentence as ERP27 in open-access papers:
ERP27 is named in the same sentence as 15 diseases in open-access papers, as found by Europe PMC text mining. Sharing a sentence is not in itself a finding about the gene and the disease. The quoted sentences say what the papers report.
acute pancreatitis (3 papers, 2014 to 2022). An acute inflammatory process that leads to necrosis of the pancreatic parenchyma. "ERP27 was shown to be down-regulated in acute pancreatitis in rats and selectively expressed in pancreatic exocrine glandular cells." (PMID 29340021, 2017). "(iv) ERP27, a member of the protein disulfide isomerase family of endoplasmic reticulum proteins and previously shown to be down-regulated in acute pancreatitis in rats, showed wide-spread cytoplasmic expression in acinar cells of human pancreas." (PMID 25546435, 2014). "Moreover, ERP27 has also been identified to be downregulated in acute pancreatitis in rats and exhibited extensive cytoplasmic expression in acinar cells of the human pancreas." (PMID 36157207, 2022).
glioma (3 papers, 2020 to 2022). A benign or malignant brain and spinal cord tumor that arises from glial cells (astrocytes, oligodendrocytes, ependymal cells). "Among them, PCOLCE2, ERP27, PSMD13, C14orf39, C16orf86, UGCG, and HPX were identified as prognostic factors for glioma for the first time." (PMID 35873494, 2022).
breast carcinoma (2 papers, 2023 to 2024). "Western-blot analysis revealed that the protein expression of FBXO6, PMAIP1, ERP27, and CHAC1were significantly higher in breast cancer cell lines(SKBR-3, MDA-MB-231, T-47D)than in normal mammary epithelial cell line MCF-10A." (PMID 37313465, 2023). "Using multivariate Cox analysis, FBXO6, PMAIP1, ERP27, and CHAC1 were identified as independent prognostic factors in patients with breast cancer." (PMID 37313465, 2023).
breast tumors (1 paper, 2023). "We compared the expression profiles of 272 ERS-related genes in primary breast tumors and normal breast tissue and identified FBXO6, PMAIP1, ERP27, and CHAC1 as independent prognostic factors with established risk models (defining the risk scores as ERScore) and model validation." (PMID 37313465, 2023).
colorectal cancer (1 paper, 2022). A primary or metastatic malignant neoplasm that affects the colon or rectum. "ERP27 is highly expressed in colorectal cancers, and its expression is correlated with patient survival." (PMID 35873494, 2022).
colorectal tumors (1 paper, 2021). "Interestingly, expression levels of ERP27 and WBP11 were significantly different between colorectal tumors and nontumor tissues." (PMID 34309201, 2021).
COVID-19 (1 paper, 2025). A disease caused by infection with severe acute respiratory syndrome coronavirus 2. "Among the 5 common DEGs, four were significantly downregulated (ERP27, SYTL5, EXTL1, DIO2) and one was upregulated (STXBP6) in the COVID-19 dataset." (PMID 40660393, 2025).
pterygium (1 paper, 2025). A wedge-shaped fibrovascular lesion arising from the bulbar conjunctiva and extending to the cornea. "A similar tendency was observed in pterygium tissues versus normal controls, with a significant decrease in the level of four genes (ERP27, SYTL5, EXTL1, DIO2) and an increment of gene STXBP6." (PMID 40660393, 2025).
rectal tumors (1 paper, 2021). "Comparison of gene expression levels using the TCGA data showed that the expression levels of ERP27 and WBP11 were higher in the colon and rectal tumors than in adjacent normal tissues (the ‘solid tissue normal’ in TCGA data)." (PMID 34309201, 2021).
cancer (4 papers, 2019 to 2024). A tumor composed of atypical neoplastic, often pleomorphic cells that invade other tissues. "Transcriptomic analysis of the cancer genome atlas has identified ERP27 as a pivotal gene in the pathogenesis and progression of PDAC." (PMID 36983764, 2023). "We analyzed the expression of the four independent prognostic factors (FBXO6, PMAIP1, ERP27, and CHAC1) in BRCA and 32 other cancer types and observed that all four genes were highly expressed in BRCA." (PMID 37313465, 2023).
ERP27 also shares sentences with these, for which no sentence is quoted: tumor (3 papers); diabetics (1); kidney cancer (1); pancreatic cancer (1); pancreatic ductal adenocarcinoma (1).